APTX (aprataxin)
Description:
DNA-binding protein involved in single-strand DNA break repair, double-strand DNA break repair and base excision repair. Resolves abortive DNA ligation intermediates formed either at base excision sites, or when DNA ligases attempt to repair non-ligatable breaks induced by reactive oxygen species. Catalyzes the release of adenylate groups covalently linked to 5'-phosphate termini, resulting in the production of 5'-phosphate termini that can be efficiently rejoined. Also able to hydrolyze adenosine 5'-monophosphoramidate (AMP-NH(2)) and diadenosine tetraphosphate (AppppA), but with lower catalytic activity. Likewise, catalyzes the release of 3'-linked guanosine (DNAppG) and inosine (DNAppI) from DNA, but has higher specific activity with 5'-linked adenosine (AppDNA) (By similarity).
Synonyms: FHA-HIT; AXA1; FLJ20157; AOA; AOA1; EAOH; EOAHA
Tractability: Small molecule: a structure with a bound ligand is known. PROTAC: ubiquitination databases record sites on it; its protein half-life has been measured.
Target class: Enzyme; Hydrolase
Gene: Protein-coding gene on chromosome 9 (32,886,601 to 33,025,130, reverse strand). Ensembl gene ENSG00000137074.
Subcellular location: Nucleus, nucleoplasm; Nucleus, nucleolus; Cytoplasm (Isoform 12)
Subcellular location (Human Protein Atlas): Nucleoli; Nucleoplasm
Gene Ontology:
Molecular function: chromatin binding; damaged DNA binding; DNA 5'-adenosine monophosphate hydrolase activity; double-stranded DNA binding; double-stranded RNA binding; phosphoglycolate phosphatase activity; phosphoprotein binding; protein binding; DNA-3'-diphospho-5'-guanosine diphosphatase activity; mismatched DNA binding; single-strand break-containing DNA binding; single-stranded DNA binding; catalytic activity
Biological process: regulation of protein stability; single strand break repair; regulation of DNA repair
Cellular component: chromatin; cytoplasm; nucleolus; nucleoplasm; DNA ligase III-XRCC1 complex; nucleus; site of DNA damage
Genetic constraint (gnomAD): Loss-of-function variants: 28 observed, 39.46 expected, observed/expected ratio (o/e) 0.71, 90% interval 0.52 to 0.97. The upper end of that interval is the gene's LOEUF score, 0.97, which puts it in group 4 of 6, group 1 being the genes least tolerant of losing a copy. Missense variants: 403 observed, 418.36 expected, observed/expected ratio (o/e) 0.96, 90% interval 0.89 to 1.05. Synonymous variants: 126 observed, 149.13 expected, observed/expected ratio (o/e) 0.84, 90% interval 0.73 to 0.98.
Homologues: Orthologues: chimpanzee APTX (99% identical), macaque APTX (98% identical), dog APTX (92% identical), pig APTX (91% identical), rabbit APTX (90% identical), guinea pig APTX (89% identical), mouse Aptx (85% identical), rat Aptx (81% identical), tropical clawed frog aptx (61% identical), zebrafish aptx (57% identical), Drosophila melanogaster Aptx (20% identical). Paralogues in human: HINT3 (13% identical).
Diseases named in the same sentence as APTX in open-access papers:
APTX is named in the same sentence as 81 diseases in open-access papers, as found by Europe PMC text mining. Sharing a sentence is not in itself a finding about the gene and the disease. The quoted sentences say what the papers report.
Ataxia (52 papers, 2006 to 2025). Ataxia refers to impaired coordination of voluntary muscle movement. "In our study, we investigated Ataxia with Oculomotor Apraxia Type 1, which is caused by pathogenic variants in the APTX gene." (PMID 38570878, 2024). "As before mentioned, among five APTX-related families in our study, three novel variants were found; these findings provide further insights into the genetic basis of Ataxia with Oculomotor Apraxia Type 1 in the study population." (PMID 38570878, 2024). "APTX mutations cause ataxia with oculomotor apraxia type 1, a neurodegenerative disorder with early-onset cerebellar ataxia, oculomotor apraxia, and severe axonal polyneuropathy." (PMID 38722242, 2024). "Clinically, patients with APTX deficiency suffer from ataxia with childhood-onset and will usually need a wheelchair by their twenties." (PMID 38161589, 2023). "There are four subtypes of ataxia with oculomotor apraxia (AOA): AOA1 [mutations in APTX and/or PNKP]; AOA2 [mutations in SETX]; AOA3 [mutations in PIK3R5]; AOA4 [mutations in PNKP]." (PMID 38161589, 2023). "Aprataxin (APTX) mutations lead to progressive ataxia-ocular motor apraxia 1 (AOA1) and peripheral neuropathy." (PMID 37762489, 2023). "APTX mutations are causative in ataxia with oculomotor apraxia 1 (AOA1), a syndrome with similar cerebellar pathology to A-T." (PMID 34910524, 2021). "In previous studies, the same research group reported that APTX truncating mutations are associated with early-onset cerebellar ataxia." (PMID 32750061, 2020). "Ataxia with oculomotor apraxia type 1 (AOA1) is a rare autosomal recessive cerebellar ataxia, caused by mutations in the APTX gene." (PMID 32750061, 2020). "Defects in aprataxin cause the autosomal recessive neurodegenerative disorder ataxia oculomotor apraxia 1 (AOA1)." (PMID 31921313, 2019). "Ataxia with oculomotor apraxia 1 (AOA1) results from an aprataxin deficiency which is associated with scaffolding proteins which facilitate accurate base-excision repair." (PMID 29641431, 2018). "APTX mutations are linked to the progressive neurodegenerative diseases ataxia with Oculomotor Apraxia 1 (AOA1), ataxia with coenzyme Q10 (coQ10) deficiency, and a multiple system atrophy resembling Parkinson's disease." (PMID 29934293, 2018). "For example, certain forms of ataxia are caused by mutations in the BER-associated gene APTX, and mutations in NER-related genes (XPA-XPG) result in xeroderma pigmentosum, both syndromes that are accompanied by higher rates of neurodegeneration." (PMID 28218666, 2017). "Mutations in the APTX (OMIM 606350) gene are associated with ataxia with oculomotor apraxia type 1 (OMIM 208920)." (PMID 28652255, 2017). "Patients with loss of functional APTX are affected by ataxia with oculomotor apraxia-1 (AOA1), with progressive cerebellar ataxia." (PMID 26942017, 2016). "The ataxia with oculomotor apraxia type 1 (AOA1) was the fifth most frequent ARCA in our cohort since we have identified 6 patients (3 families) carrying APTX mutations, although it seems to be a rare condition outside Japan or Portugal." (PMID 26068213, 2015). "Aprataxin (APTX) deficiency causes progressive cerebellar degeneration, ataxia and oculomotor apraxia in man." (PMID 25274775, 2015). "Defects in aprataxin cause the autosomal recessive neurodegenerative disorder Ataxia Oculomotor Apraxia 1 (AOA1), which accounts for ∼10% of autosomal recessive cerebellar ataxias." (PMID 25274775, 2015). "Ataxia with oculomotor apraxia type 1 is caused by bi-allelic mutations in APTX (chromosome 9p21.1)." (PMID 26285866, 2015). "The first causative mutations identified in the ataxic form of CoQ10 deficiency were detected in APTX, which encodes aprataxin and is the causative gene for ataxia with oculomotor apraxia 1 (AOA1)." (PMID 25182700, 2014). "The reason why ATM and APTX deficiency is required to generate ataxia in mice, when loss of either is sufficient to cause ataxia in humans, remains unclear." (PMID 34723800, 2021).
Ataxia (continued). "Studies have confirmed that APTX mutations are involved in the degeneration of Purkinjie and cerebellar granular cells which are the most critical pathophysiological features responsible for cerebellar atrophy and ataxia." (PMID 32750061, 2020). "APTX deficiency causes progressive cerebellar degeneration, ataxia and oculomotor apraxia in man." (PMID 25274775, 2015). "Interestingly, in one of our patients, seizures disappeared after CoQ10 supplementation, as previously reported in a patient with CoQ10 deficiency and cerebellar ataxia due to APTX mutations." (PMID 25182700, 2014). "We screened nine affected individuals from 4 families with ataxia and oculomotor apraxia for mutations in the reported genes APTX, SETX and MRE11 and identified a novel truncating mutation in SETX gene in one family and a previously reported missense mutation in MRE11 gene in two families." (PMID 21324166, 2011). "Recently, a homozygous mutation in the aprataxin gene in a family with coenzyme Q10 deficiency and cerebellar ataxia has been reported, suggesting also that coenzyme Q10 may participate in the pathogenesis of AOA1." (PMID 17112370, 2006). "During his life, the patient underwent extensive targeted testing for known genes associated with ataxia and spasticity (spastic paraplegias 3A, 4, and 7; spinocerebellar ataxias 1, 2, 3, 6, 7, and 14; FXN‐, APTX‐, SETX‐, PLP1‐, and LCFA‐related disorders)." (PMID 34753215, 2022). "APTX removes an adenylate (AMP) from the 5′-end of ligation failure products and its deficiency is linked to the neurodegenerative ataxia disorder Ataxia-oculomotor apraxia 1 (AOA1)." (PMID 34339737, 2021). "Here, we report new disease-relevant murine models of genome instability–driven neurodegeneration involving disabled ATM and APTX that develop debilitating ataxia." (PMID 34910524, 2021). "It has been reported that a deficiency of XRCC1 leads to a reduction in APTX accumulation at the sites of DNA damage, and furthermore, XRCC1 mutations have been found to be associated with cerebellar ataxia, ocular motor apraxia, and axonal neuropathy." (PMID 34339737, 2021). "This study confirmed the need of WES to assist in the diagnosis of cerebellar ataxia and it emphasizes the importance of studying the pathophysiology of the APTX gene." (PMID 32750061, 2020). "Mutations in multiple DNA replication and repair genes such as TCD1, PNKP, XRCC1, and APTX result in ataxia, highlighting the central role of this pathway in these overlapping disorders." (PMID 31230722, 2019). "Using WES in a large consanguineous family, we identified a novel homozygous stop-gain mutation (c.739A>T) in the APTX gene, leading to a diagnosis of ataxia with AOA1." (PMID 28652255, 2017). "In our survey ~60% of juvenile-to-adult cases with cerebellar ataxia, sensorimotor neuropathy and increased AFP are due to mutations in the SETX gene, and a smaller percentage to APTX and ATM gene mutations." (PMID 23941260, 2013). "In this study, we performed a mutational screening of ATM, APTX, SETX in a selected cohort of twenty-two Italian patients presenting cerebellar ataxia, sensorimotor axonal neuropathy, and elevated AFP." (PMID 23941260, 2013). "Furthermore, mutations in APTX gene cause recessively inherited neurodegenerative disorders, such as ataxia oculomotor apraxia 1 (AOA1) and early onset ataxia with oculomotor apraxia and hypoalbuminemia (EAOH)." (PMID 36940705, 2023). "Like prior ATM-deficient A-T mouse models, ATM or APTX deficiency alone did not result in mice with ataxia." (PMID 34723800, 2021). "Our results indeed demonstrate that mice deficient in ATM and APTX develop cerebellar dysfunction, atrophy, and a progressive and profound ataxia, while mice deficient in either protein alone do not." (PMID 34723800, 2021).
Ataxia (continued). "Importantly, several DNA-end processing enzymes recruited by XRCC1 are mutated in human ataxias, such as the spinocerebellar ataxia with axonal neuropathy-1 (SCAN1; mutated in TDP1), ataxia oculomotor apraxia-1 (AOA1; mutated in aprataxin) and ataxia oculomotor apraxia-4 (AOA4; mutated in PNKP)." (PMID 30991935, 2019). "Cells lacking Aprataxin show increased levels of DNA breaks and the human disease characterized by Aprataxin deficiency is associated with progressive cerebellar degeneration, ataxia and oculomotor apraxia." (PMID 26455503, 2016). "Consistent with the behavioral results, cerebellar dysfunction was found only in the AtmR35X/R35X; Aptx−/− mice that developed ataxia and not in mice with partial or full expression of ATM or APTX." (PMID 34723800, 2021). "Ataxia with oculomotor apraxia defines a group of genetically distinct recessive ataxias including ataxia-telangectasia (A-T, ATM gene), ataxia with oculomotor apraxia type 1 (AOA1, APTX gene) and type 2 (AOA2, SETX gene)." (PMID 23941260, 2013). "Lack of mutations in APTX, SETX and MRE11 genes in the third family diagnosed with ataxia and oculomotor apraxia and no cerebellar atrophy suggests the involvement of another mechanism for the development of this disorder." (PMID 21324166, 2011). "Molecular studies of frataxin and aprataxin genes ruled out Friedrich ataxia and cerebellar ataxia with oculomotor apraxia 1 (AOA1)." (PMID 21392394, 2011).
Oculomotor apraxia (18 papers, 2006 to 2023). Ocular motor apraxia is a deficiency in voluntary, horizontal, lateral, fast eye movements (saccades) with retention of slow pursuit movements. "For instance, mutations of SSB repair gene APTX lead to oculomotor apraxia-1 (AOA1), in which cerebellar atrophy caused by a severe loss of Purkinje cells are characterized along with oculomotor apraxia." (PMID 35153719, 2021). "Mutations in APTX cause an inherited human disease syndrome characterized by early-onset progressive ataxia with ocular motor apraxia (AOA1)." (PMID 26256098, 2015).
ataxia with oculomotor apraxia type 1 (12 papers, 2009 to 2024). "Mutations in the APTX gene lead to ataxia oculomotor apraxia type 1 (AOA1)." (PMID 24637776, 2014). "Interestingly, some cases of the ataxic variant of CoQ10 deficiency have been linked to a homozygous mutation in the aprataxin (APTX) gene, which causes ataxia oculomotor apraxia type 1." (PMID 27713230, 2009). "Decreased APE1 levels were found in patient cells affected by Ataxia with Oculomotor Apraxia Type 1 (AOA1), a neurodegenerative disorder originating in mutations of the APTX gene, which results in a cellular aprataxin deficiency." (PMID 23203191, 2012). "Other relatively common recessive ataxias include ataxia telangiectasia (A-T), ataxia with oculomotor apraxia type 1 (AOA1) and ataxia with oculomotor apraxia type 2 (AOA2), caused by mutations in the ATM-, APTX- and SETX-genes respectively, all of which encode proteins involved in DNA-repair." (PMID 35061740, 2022).
ataxia telangiectasia (11 papers, 2013 to 2024). Ataxia-telangiectasia is the association of severe combined immunodeficiency (affecting mainly the humoral immune response) with progressive cerebellar ataxia. "Interestingly, APTX mutations also lead to mild radiosensitivity, a phenotype likewise shared by ataxia telangiectasia patients, which could be directly correlated with DNA repair defects." (PMID 38161589, 2023). "Ataxia Telangiectasia (A-T) and Ataxia with Ocular Apraxia Type 1 (AOA1) are devastating neurological disorders caused by null mutations in the genome stability genes, A-T mutated (ATM) and Aprataxin (APTX), respectively." (PMID 34723800, 2021).
Ataxia oculomotor apraxia-1 (7 papers, 2009 to 2025). "Ataxia oculomotor apraxia-1 (AOA1) is a rare and inherited neurological disorder caused by mutations in the gene (APTX) encoding aprataxin." (PMID 41153405, 2025). "Ataxia with oculomotor apraxia-1 (AOA1) is caused by mutations in aprataxin (APTX), spinocerebellar ataxia with axonal neuropathy-1 (SCAN1) is derived from mutated Tyrosyl-DNA Phosphodiesterase 1 (TDP1)." (PMID 31110700, 2019). "For example, mutations in MRE11, TDP1 and aprataxin (APTX) result in neurodegenerative disorders such as A-T like disease (ATLD), spinocerebellar ataxia with axonal neuropathy (SCAN1), and ataxia-oculomotor apraxia-1 respectively." (PMID 32284789, 2020). "Ataxia oculomotor apraxia-1 (AOA1) is an autosomal recessive neurodegenerative disease that results from mutations of aprataxin (APTX)." (PMID 19303373, 2009). "Indeed, mutation of the genes encoding DNA ligase IV (LIG4), Nibrin (NBS1) or Aprataxin (APTX) results in DDR disorders, specifically LIG4 syndrome, Nijmegen breakage syndrome (NBS) and Ataxia oculomotor apraxia-1, in association with increased radiosensitivity." (PMID 26208712, 2015). "Interestingly, impairment of DNA ligase IV (LIG4), nibrin (NBS1), or aprataxin (APTX) activity as a result of genes’ deleterious mutation leads to severe disorders in DNA damage response known as LIG4 syndrome, Nijmegen breakage syndrome (NBS), and Ataxia oculomotor apraxia-1." (PMID 36340042, 2022).
Cerebellar atrophy (7 papers, 2011 to 2021). Cerebellar atrophy is defined as a cerebellum with initially normal structures, in a posterior fossa with normal size, which displays enlarged fissures (interfolial spaces) in comparison to the foliae secondary to loss of tissue. "L248M: The dominant L248M APTX mutant was identified in AOA1 patients with severe clinical phenotype presenting early disease onset and a progressive ataxic syndrome with cerebellar atrophy, mental retardation, and epilepsy." (PMID 29934293, 2018).
coenzyme Q10 deficiency (4 papers, 2006 to 2025). A genetically heterogeneous condition, typically inherited in an autosomal recessive fashion, characterized by coenzyme Q10 deficiency. "The relationship between aprataxin, involved in DNA repair, and coenzyme Q10 deficiency, if any, is still unclear." (PMID 25145890, 2014). "In contrast, secondary coenzyme Q10 deficiency, due to mutations in genes not directly related to ubiquinone biosynthesis (i.e. APTX, ETFDH, BRAF), has been identified in patients with CA, pure myopathy and cardiofaciocutaneous syndrome." (PMID 25145890, 2014).
Hypoalbuminemia (4 papers, 2015 to 2023). The concentration of albumin in the blood circulation is below the lower limit of normal. "AOA1 (MIM#208920) caused by mutations in APTX encoding aprataxin is characterized by hypoalbuminemia and hypercholesterolemia." (PMID 27165045, 2017).
cervical cancer (2 papers, 2016 to 2017). A primary or metastatic malignant neoplasm involving the cervix. "Studies show that increased APTX expression was closely associated with anticancer drug resistance in cervical carcinoma cells." (PMID 27769049, 2016). "To investigate the mechanism of miR-424 in regulating cervical cancer cell radiosensitivity, we used algorithms that predict mRNA targets of miRNAs that have been identified as candidates for miR-424, and we choose APTX as a putative target gene for miR-424." (PMID 27769049, 2016). "Furthermore, we identified that miR-424 exhibits its biological function through directly inhibiting the expression of APTX in cervical cancer cells." (PMID 27769049, 2016). "In addition, enhanced radiosensitivity by miR-424 was abolished by ectopic expression of APTX in cervical cancer cells." (PMID 27769049, 2016). "We also identified that aprataxin (APTX) is a target of miR-424 in cervical cancer." (PMID 27769049, 2016). "Here, we also investigated whether APTX directly contributes to the role of miR-424 for radioresistant cervical cancer cells." (PMID 27769049, 2016). "Additionally, APTX overexpression blocked miR-424, and IR-treatment induced cell cycle arrest, suggesting that APTX is the major contributor to the effects of miR-424 on cervical cancer cell radiosensitivity." (PMID 27769049, 2016). "Taken together, these data suggest that APTX is target gene of miR-424 in cervical cancer." (PMID 27769049, 2016). "In addition, we identified a negative correlation between miR-424 and APTX expression in specimens from patients with cervical cancer." (PMID 27769049, 2016). "However, there is no direct evidence for the role of APTX in cervical cancer radiosensitivity." (PMID 27769049, 2016).
Cockayne syndrome (2 papers, 2013 to 2025). A multisystem condition characterized by short stature, a characteristic facial appearance, premature aging, photosensitivity, progressive neurological dysfunction, and intellectual deficit. "It interacts with various repair proteins involved in BER and nucleotide excision repair (NER), such as Polγ, EXOG1, TFAM, Cockayne syndrome B (CSB), aprataxin (APTX), and tyrosyl‐DNA phosphodiesterase 1 (TDP1)." (PMID 40418056, 2025).
colon cancer (2 papers, 2012 to 2013). "It has been reported that colon cancer patients with lower levels of APTX might be more sensitive to CPT-11 based chemotherapy." (PMID 23762305, 2013).